CXCL10 (C-X-C motif chemokine ligand 10)
Diseases named in the same sentence as CXCL10 in open-access papers (continued):
Sharing a sentence is not in itself a finding about the gene and the disease.
tumor (continued). "In a mouse LLC tumor model, intravenous injection of such NP significantly reduced tumor volume and increased CXCL9, CXCL10, and CXCL11 protein levels in tumor tissues." (PMID 40124344, 2025). "OVs secrete chemokines, such as CXCL9 and CXCL10, which attract CAR-T cells into the tumour core, thereby enhancing T cell homing into the tumour site." (PMID 40624498, 2025). "In contrast, ELR-negative chemokines such as CXCL9, CXCL10, and CXCL11 are classically viewed as anti-tumor agents due to their angiostatic and immune modulatory effects mediated by their shared receptor, CXCR3." (PMID 41516196, 2025). "For example, IL-15 sustains NK cell survival and cytotoxicity via mTOR activation, whereas the chemokines CXCL10 and CXCL11 recruit NK cells to tumour margins." (PMID 41429765, 2025). "RCN6 was mainly localized in tumor stroma, where CAF-FAP was spatially proximal to t_MP5, CD8_PDCD1, neutrophil, Monocyte_CD14, and Macrophage_CXCL10, which featured by inflammation and immune exhaustion." (PMID 39870619, 2025). "Radiotherapy can also modulate the tumour microenvironment by increasing the expression of chemokines such as CXCL9 and CXCL10, which attract CAR-T cells to the tumour site." (PMID 40906384, 2025). "Serum HMGB1 levels reflect tumor cell lysis and ICD-driven DC activation, whereas CXCL9/CXCL10 gradients predict Batf3-dependent CD103+ DC migration and T-cell priming." (PMID 40989107, 2025). "Signature gene analysis of IFN‐Mac_CXCL9 revealed 108 significantly up‐regulated genes in tumour‐infiltrating cells including HLA‐A, HLA‐DRB1 and interferon‐regulated genes (CXCL9, CXCL10 and IL4I1)." (PMID 41275425, 2025). "Through in vitro and in vivo experiments, we disclosed that NCD upregulates the TIME-GES genes CXCL10, CXCL11, EBI3, and FLT3LG, promotes CD8+ T cell activation and tumor infiltration, thereby inhibiting the growth of TNBC." (PMID 41293150, 2025). "At the same time, IκBζ simultaneously repressed several other chemokines, known to regulate recruitment of T cells and NK cells into the tumor microenvironment, such as CXCL9, CXCL10, and CCL546." (PMID 40562773, 2025). "Understanding the complex relationship between CXCL10, the JAK-STAT pathway and immune checkpoints provide valuable insights for the development of targeted therapies aimed at reprogramming the tumor microenvironment and improving cancer treatment outcomes." (PMID 40760734, 2025). "Bacterial components activated chemokine production (e.g., CXCL9, CXCL10, CCL5) by tumor cells, thereby enhancing T cell infiltration." (PMID 40475782, 2025). "The interaction between chemokines (e.g., CCL7, CXCL3, CXCL10, and CXCL6) on Teff cells and their receptors attracts effector CD8+ T cells to rapidly migrate to inflammatory sites or tumor tissues, amplifying the inflammatory response." (PMID 41281945, 2025). "The interaction between chemokines such as CXCL9, CXCL10, CXCL11, and their receptor CXCR3 is known to affect immune cell behavior, potentially enhancing tumor growth and spread." (PMID 39964621, 2025). "Subsequently, we examined the mRNA levels of CCL5, CD274, CXCL10, CXCL11, and CCL2 in MDA‐MB‐231 and 4T1 cells and tumor tissues." (PMID 39585774, 2025). "Activation of this pathway results in the release of chemokines such as CCL5, CXCL9, and CXCL10, which recruit immune cells—including CD8+ T lymphocytes, macrophages, and dendritic cells—into the tumour microenvironment." (PMID 40596709, 2025). "Second, tumor‐homing eosinophils secrete chemokines such as CCL5, CXCL9, and CXCL10 that create chemotactic gradients for cytotoxic T lymphocytes." (PMID 41362643, 2025). "Conditioned media from CXCL10- and CXCL11-expressing tumour cells significantly enhanced CAR T cell migration compared with media from control tumour cells using two distinct transwell migration assays." (PMID 41366257, 2025).
tumor (continued). "In a mouse model of bone metastasis, systemic treatment with a neutralizing anti-CXCL10 antibody significantly reduced the migration of CXCR3-expressing cancer cells to the bone and decreased overall tumor burden." (PMID 41516196, 2025). "Specific factors in SASP (e.g., CXCL10, TRAIL) activate immune surveillance and recruit natural killer cells and cytotoxic T lymphocytes to clear tumor cells." (PMID 41048400, 2025). "Despite these factors, we found that lung macrophages isolated from lung biopsies taken at sites distant from the tumor exhibited corticosteroid sensitivity, as evidenced by reduced expression of CXCL9, CXCL10, and CXCL11." (PMID 41229420, 2025). "CXCL9, CXCL10, and CXCL11 interact with CXCR3 on tumor cells, immune cells, and vascular endothelial cells, influencing tumor growth, immune cell activity, and blood vessel formation." (PMID 40362215, 2025). "By targeting CXCL10 with ‎CRISPR, researchers can fine-tune ‎‎immune responses and specifically inhibit angiogenesis, ‎leading to a more controlled and tumor-‎specific therapeutic effect." (PMID 40760734, 2025). "Concurrently, N1 TANs amplify anti-tumor immunity by recruiting CD8+ T cells via chemokines such as CXCL10 and CCL3, facilitating antigen-specific tumor clearance." (PMID 41438763, 2025). "T-cells regulatory (Tregs), M0 macrophages, and M1 macrophages are co-owned by CXCL10 and CXCL11, suggesting that they can provide help in tumor immunotherapy of PAAD." (PMID 40129606, 2025). "Our study has detailly demonstrated the synergistic mechanism of CXCL10 and CXCL11 in the ELR-negative CXC chemokines gene family in the tumor microenvironment and immune infiltration of PAAD." (PMID 40129606, 2025). "Activation of NF-κB can drive the production of chemokines such as CXCL10, which promotes CD8+ T cell infiltration and improves the anti-tumor response." (PMID 41050935, 2025). "CXCL8 and CXCL10 promote ECM degradation by inducing overexpression of MMP-2 and MMP-9, thereby creating a gateway for tumor cell invasion." (PMID 41445742, 2025). "Chemokines such as CXCL4, CXCL9, CXCL10, CXCL11, CXCL13, and CCL5 contribute to the accumulation of CD8+ T cells and B lymphocytes in tumor tissues and inhibit angiogenesis." (PMID 41223031, 2025). "Some of them, such as CCL5, CXCL10, and CXCL9, are produced by DCs upon activation to favor tumor T cell recruitment." (PMID 40578365, 2025). "In LLC cells, CRTC1 upregulated tumor cell PD-L1 expression, suppressed T cell-derived IFN-γ and IL-2 production, diminished endogenous CXCL10/11 secretion, and impaired T cell proliferation and cytotoxicity." (PMID 40977688, 2025). "On the other hand, chemokine CXCL10 transcribed by STAT1 recruited more CD8+ T cells, especially TEFF, into the tumor local immunological milieu." (PMID 40315321, 2025). "The results from ELISA demonstrated an upregulation of CXCL10 expression in both 4MOSC1 and MC38 tumours." (PMID 39219056, 2025). "Motile tumour cells frequently overexpress MMPs, such as MMP-8 and MMP-9, which cleave chemokines like CXCL9 and CXCL10, disrupting chemotactic gradients and diminishing T-cell infiltration." (PMID 40361472, 2025). "They found that the modified OMVs specifically target tumor tissue in vivo, triggering interferon-γ (IFN-γ) and C-X-C motif chemokine ligand 10 (CXCL10) to stimulate a strong, sustained immune response that clears tumors." (PMID 40159726, 2025). "CXCR3, a common receptor for CXCL9 and CXCL10 recruits Th1 cells to the TME, suppressing tumour growth." (PMID 40852716, 2025). "Monoclonal antibodies against CXCL10 and inhibitors of CXCR3 significantly reduced T cell count of both eosinophil-tumor coculture group." (PMID 40025520, 2025). "Key immune activation and tumor suppression genes including CD2, CD3, CD247 (CD3 zeta chain), CD48, CD84, CCL19, CXCL10, and SLAMF6 were consistently upregulated in the hot phenotype across all ancestries." (PMID 41387728, 2025).
tumor (continued). "The IFNγ pathways shared the downstream IRF1 and STAT1 molecules that bound with the promoters of PD-L1 and CXCL10, enhancing the efficacy of anti-PD1/PD-L1 inhibitors and boosting T-cell infiltration in the tumor microenvironment." (PMID 40149259, 2025). "This process requires the production of appropriate chemokines by the endothelial cells and tumor stroma, namely CXCL9, CXCL10, CXCL11, and CCL5." (PMID 41008910, 2025). "The role of CXCL10 and its receptor CXCR3 in tumorigenesis and tumor progression was complex and multifaceted." (PMID 40129528, 2025). "Neutrophils contribute to the establishment of pre-metastatic niches by secreting chemokines such as ARG1, CXCL1, CXCL2, CXCL10, CCL2, CXCR2, and vascular endothelial growth factor A (VEGFA), which attract tumor cells to metastatic sites." (PMID 40227814, 2025). "While some CXC chemokines act as tumor promoters in MM, others, like CXCL4 and CXCL10, impede malignant cell growth." (PMID 38475811, 2024). "Epigenetic silencing of the tumor Th1-type chemokines CXCL9 and CXCL10 also contributes to severe T-cell infiltration and greater tumor evasion." (PMID 38791528, 2024). "Mechanistically, we show that IGF blockade promotes macrophage and fibroblast production of the chemokines CXCL9 and CXCL10 to facilitate CD8+ T cell recruitment and trafficking towards the PDAC tumour." (PMID 39165364, 2024). "Initially TNF-γ works by recruiting cohorts (CXCL9, CXCL10, CXCL11, and CXCR3) to promote antigen presentation (MHC class I and class II), T-cell initiation and activation (CD80, CD86, and CD40), and tumor cell killing (Fas and FASL)." (PMID 39835116, 2024). "Through the utilization of CellChat analysis, we observed that outgoing signals from CXCL10+ M1 macrophages to B cells, CD4+ T cells, CD8+ T cells was noticeably enhanced within the tumor group." (PMID 39170612, 2024). "Analysis of the MDMs demonstrated that IFNG neutralization diminished induction of CXCL9, CXCL10 and CXCL11 gene expression in MDMs in both tumor model systems." (PMID 39414902, 2024). "Single-cell RNA-sequencing analysis of patient tumor-infiltrating lymphocytes revealed that CXCR3 was expressed by CD8+ and CD4+ T cells, whilst CXCL9 and CXCL10 were predominantly expressed by macrophages following dual ICI treatment." (PMID 38533720, 2024). "CXCL10 expression and its pathway components, NLRP3, NF-κB, and IL-1β, were markedly suppressed in tumor tissues from the calycosin-treated mice." (PMID 38461458, 2024). "EC-C4 highly expressing DPP4 interacted with TAMs expressing chemokines CXCL10 and CXCL11, especially CXCL11+ TAMs, thereby inhibiting their anti-tumor immune response." (PMID 39232806, 2024). "Additionally, we found that PD-L1 and its regulators were universally up-regulated in tumor-derived CXCL10+ cDCs compared with non-tumor-derived cDCs, suggesting that CXCL10+ cDCs might cause T cells to differentiate into regulatory T cells via PD-1/PD-L1, thereby suppressing anti-tumor immunity." (PMID 39104420, 2024). "In human breast cancer cells, the expression and secretion of CXCL10, a newly identified SASP factor, promoted ECM invasion and tumour progression." (PMID 39270064, 2024). "Therefore, CXCL10 may recruit T lymphocytes in the tumor microenvironment." (PMID 38953994, 2024). "For CD8+ T cells to effectively infiltrate the tumor site, chemokine receptors, such as CXCR3, must interact with their corresponding chemokines (CXCL9, CXCL10 and CXCL11)." (PMID 39409972, 2024). "CXCL4, CXCL10, and CXCL11 are known to inhibit angiogenesis and cell proliferation, thus targeting the angiogenic nature of the tumor microenvironment." (PMID 38339062, 2024). "Cxcr3, a chemokine receptor with anti-tumor effects expressed in effector CD8+ T cells, Th1 cells, and NK cells, interacts with its ligands Cxcl9, Cxcl10, and Cxcl11, promoting immune cell recruitment to TME." (PMID 38622609, 2024).
tumor (continued). "In conclusion, CXCL10, which directly polarizes and potentiates CXCR3+ CD8+ T cells, also directly potentiates these cells to limit tumor growth." (PMID 39474427, 2024). "The extensively diffusion of this cytokine alters the tumor microenvironment through the induction of CXCL9, CXCL10, and CXCL11, which recruit effect immune cells such as natural killer (NK) cells, T cells, monocytes, and others to the tumor site." (PMID 39080467, 2024). "In our study, four macrophage subsets were identified in primary tumor and metastatic specimens: SPP1+ macrophages, C1QC+ macrophages, CXCL10+ macrophages and FOLR2+ macrophages." (PMID 38519500, 2024). "In contrast to tumor gene expression, the levels of systemic CCL5, CXCL9 and CXCL10 in baseline serum samples were similar among all patients, regardless of their response to anti-HER2 antibody-based neoadjuvant treatment." (PMID 38167224, 2024). "Following YY001 treatment, the tumor tissue exhibited increased secretion of cytokines such as CXCL9, CXCL10, and CXCL11, which contribute to the recruitment of more T cells." (PMID 38560505, 2024). "The CXCL9, CXCL10 and CXCL11/CXCR3 axes have been demonstrated to regulate immune cell migration, differentiation, and activation, leading to tumour suppression." (PMID 39233332, 2024). "Exercise-induced elevation of EPI is involved in the regulation of Ccl5 and Cxcl10 levels further leading to enhanced CD8+ T cell infiltration and ultimately inhibiting tumor progression." (PMID 38622609, 2024). "Chemokines can serve pro- or anti-tumor functions, with the chemokines CXCL9 and CXCL10, ligands for CXCR3, being of the most interest in the anti-tumor category due to their ability to attract effector CD8+ and CD4+ T cells." (PMID 38803496, 2024). "Tumor resident cDC1 is also the main producers of CXCL9 and CXCL10 chemokines that promote the recruitment of CD8 + T cells to the tumor microenvironment." (PMID 38231450, 2024). "This identified multiple tumour ligands, whose expression was correlated with cellular infiltrates, for further exploration in HGSOC (e.g., expression of CXCL10 correlated with RCTD scores for CXCR3-expressing T cells)." (PMID 38570491, 2024). "The levels of CXCL10, CXCL9, and CXCL11 in the tumor correlates with the concentration of intratumoral cytotoxic lymphocytes (CTLs) and reduced tumor angiogenesis." (PMID 38726320, 2024). "CAFs can regulate tumor microenvironment by releasing cytokines (IL-6) and chemokines (CCL2 and CXCL10)." (PMID 38896161, 2024). "Tumor vaccination with CXCL9/10-DC induced a statistically significant elevation in the concentrations of CXCL9 and CXCL10 within the TME at 24 h, surpassing levels observed with PBS control and Mock-DC." (PMID 38518770, 2024). "Upregulation of CXCL10 in the HL_HPS_R tumor and upregulation of CXCL11 in the HL_HPS_L tumor seem relevant since they act as key immunological chemoattractant during inflammatory responses." (PMID 39339213, 2024). "CXCL10 is a potent chemoattractant for lymphocytes including NKT cells, increasing immune cell tumor infiltration and immunotherapy efficacy." (PMID 38750591, 2024). "Accordingly, the mRNA expression of IFNβ, CXCL10, ISG15, and IFIT1 in the tumor tissues was analyzed." (PMID 39170700, 2024). "In line with previous studies, our current research found that CXCL10 activates pro-angiogenic and pro-growth signals, such as ERK, AKT, JAK2, and CREB, potentially mediated by CXCR3-A, which lead to increased B16F10 tumor growth and angiogenesis." (PMID 39268223, 2024). "CXCL9, CXCL10, and CXCL11 are mainly secreted by myeloid lineages and tumor cells in the TME responding to IFN-γ, and this process is synergistically enhanced by TNF-α." (PMID 39076974, 2024). "IFNγ-inducible chemokines CXCL9 and CXCL10 are ligands for CXCR3, a receptor expressed by diverse immune populations and reported to play important roles in immune cell recruitment and tumor immunity." (PMID 38454126, 2024).
tumor (continued). "The results indicated that CXCL10 and ISG15 were up-regulated in LUAD, LIHC, and COAD compared to the non-tumor group." (PMID 38953994, 2024). "Our results showed that the expression of CXCL9, CXCL10, GZMA, GZMB, PRF1 and IFNG was significantly higher in tumor tissues than in adjacent normal tissues in GC patients." (PMID 39376571, 2024). "Concurrently, KTC1101 treatment influences the expression of tumor-derived immunomodulatory factors like CCL5 and CXCL10 that determine T-cell infiltration." (PMID 38486218, 2024). "Literature suggests that the chemotactic draw of effector T cells into tumor sites, orchestrated by CXCL9 and CXCL10, aids in the establishment of a “hot” TME characterized by T cell inflammation." (PMID 39170612, 2024). "CXCL10 derived from tumor provides a key link between tumor cells and CD8+ T cells 50, 51 and promotes anti-tumor immune responses." (PMID 39346534, 2024). "In the context of ICIs, these drugs are thought to act primarily on T cells, stimulating them to secrete IFN-γ, which in turn reduces endothelial VEGFA and increases the levels of CXCL-9, CXCL-10, and CXCL-11, contributing to tumor vascular normalization." (PMID 39850892, 2024). "The chemokines CXCL9, CXCL10, and CXCL11 are generally produced by activated macrophages and dendritic cells to facilitate CD8+ T cell infiltration to injured or tumor tissues." (PMID 39324134, 2024). "Tumor cells with high levels of FAT2 expression also show a significant upregulation of the chemokine genes, including CCL2, CCL3, CCL4, CCL19, CXCL10, and CXCL11, in lung adenocarcinoma tissues." (PMID 38303018, 2024). "In contrast, CXCL10 was shown to increase infiltration of CD8 + T cells, increasing migration and activation of immune cells in the tumor microenvironment." (PMID 38172127, 2024). "Chemotherapy can trigger the release of the chemokine CXCL10 and the rapid secretion of type I IFNs, which can recruit CD8 + and CD4 + effector T cells to tumor sites and boost antitumor immunity." (PMID 38549044, 2024). "Ferroptosis in non-malignant hepatocytes induces an anti-tumor response through CXCL10 secretion, stimulating cytotoxic CD8+ T cells into the tumor." (PMID 38540172, 2024). "As reported, CXCL10 can recruit both immunoactive cells such as CD8+T cells and CD4+T cells, and immuosuprresive cells like MDSCs into the tumor microenvironment." (PMID 38951890, 2024). "It is believed that tumor cells evolved to express some chemokine receptors, such as CXCR3, and secrete its ligand CXCL10." (PMID 38495500, 2024). "The results demonstrated an upregulation of both RIG-I and MHC-I in tumor tissues following intratumoral injection of isiBCL-2, along with elevated levels of IFN-β and CXCL10." (PMID 38685028, 2024). "Natural killer (NK) cells can migrate quickly to the tumor site to exert cytotoxic effects on tumors, and some chemokines, including CXCL8, CXCL10 or and CXCL12, can regulate the migration of NK cells." (PMID 38727264, 2024). "Another important chemotactic NK cell receptor is CXCR3, which binds to the IFN-γ-induced and tumor-secreted CXCL9, CXCL10, and CXCL11 chemokines." (PMID 39339180, 2024). "On the opposite side, VEGF-A suppresses pro-inflammatory T-cell infiltration into the tumor through inhibition of NF-κB and TNF-α-induced downregulation of CXCL10 and CXCL11." (PMID 38726320, 2024). "The visualization results of overall information flow revealed that the information flow from CXCL10+ M1 macrophages and CD4+T cell was significantly increased in the tumor group." (PMID 39170612, 2024). "It is noteworthy to mention that tumor-infiltrating cDC1s are the major producers of CXCL9 and CXCL10 chemokine ligands that facilitate the recruitment of CD8+ T cells into the TME." (PMID 38360737, 2024).